CD276 (CD276 molecule)
Diseases named in the same sentence as CD276 in open-access papers (continued):
Sharing a sentence is not in itself a finding about the gene and the disease.
tumor (continued). "The anti-tumor effect of CD276 Dash CAR-T at the high doses (1E7 CAR-T cells) was similar to that of conventional CAR-T, but the mice died at about 40 days after CAR-T injection due to the rapid and massive expansion of CD276 Dash CAR-T in vivo." (PMID 38978106, 2024). "In this study, our primary focuses were on examining the safety and anti-tumor activity of CD276 CAR-T and addressing the challenge of lengthy CAR-T manufacturing time." (PMID 38978106, 2024). "In conclusion, CD276 was confirmed to fulfill a crucial role in mediating the inflammatory response and regulating the tumor immune microenvironment." (PMID 36717836, 2023). "During the development and metastasis of human neural crest cells (HNCCs), CD276+ CSCs are found to be located at infiltrating tumor sites and evade anti-tumor immunity by hindering the infiltration of CD8+ T cells." (PMID 36810098, 2023). "Subsequently, 9464D-WT (CD276 WT) and 9464D-KO (CD276 KO) tumor cells were injected subcutaneously on opposite flanks of syngeneic C57BL/6 mice." (PMID 38019654, 2023). "Compared to the non-tumor tissues, the expression levels of CD276 in all subgroups and CD24 in SHH, Group 3, and Group 4 subgroups are significantly higher." (PMID 36825029, 2023). "Recently, a study revealed that CD276-targeted photodynamic therapy combined with PD-L1/PD-1 axis inhibition generated local and systemic antitumour responses not only against primary tumours but also against disseminated metastases." (PMID 37974070, 2023). "And CD200 (OX-2), on the other hand, is a cell surface glycoprotein that confers immune escape by suppressing the alloimmune and autoimmune responses through its receptor CD200R.B7-H3 (CD276) is overexpressed in a variety of tumor types." (PMID 36923439, 2023). "The immune based investigation delineated the immune characteristics of DC, and disclosed the potential actions of anti-CD248 in the Cold tumor cluster, and anti-CD276 or CAR-T/CD276 in the Hot tumor cluster, providing a clinic direction for DC." (PMID 36991000, 2023). "Flow cytometry results showed a lower CD276 expression on tumor xenografts-derived Rh4 cells, with a fluorescence intensity 14-fold higher than the control, compared to cultured Rh4 cells (600-fold over control)." (PMID 37924157, 2023). "In order to further explore CD276 expression for paired normal and tumor tissues, TCGA database was employed." (PMID 36717836, 2023). "CD276 has been identified as a promising and attractive target for immunotherapy of cancers due to its abnormal upregulation in many types of tumours and participation in tumour progression." (PMID 37974070, 2023). "One study indicated that, in a variety of cancers, activated MYC in tumor cells participates in miR-29c-3p-targeted CD276 signaling to mediate immune surveillance, thereby avoiding NK-cell cytotoxicity." (PMID 36966168, 2023). "CD276, also known as B7-H3, belongs to the immune modulatory factor family that includes PD-L1 (B7-H1), which is involved in the regulation of the immune response to tumour cells." (PMID 37974070, 2023). "Pyrrolobenzodiazepine-conjugated CD276 ADCs can kill cancer cells and tumor vasculature, eradicate large tumors and metastases, and improve OS." (PMID 36797708, 2023). "B7-H3 (CD276), an immune checkpoint molecule, is associated with a poor prognosis and enhances tumor immune evasion and metastatic potential." (PMID 37020537, 2023). "It has been shown, that CD276 expression on the surface of tumor stem cells can promote their evasion of immune responses and epithelial mesenchymal transformation." (PMID 36741965, 2023). "The hyper-activation of T cell infiltration and overrepresentation of CD276 implicated the potential clinical strategies of CD276 and other CAR-T applications for the Hot tumor cluster." (PMID 36991000, 2023). "CD276 was overexpressed in all subgroups compared to the non-tumor tissues, like in our Brazilian dataset." (PMID 36825029, 2023).
tumor (continued). "As an immune-regulating member of the B7 family, a tumor cell surface molecule, and a tumor vessel endothelial marker, CD276 has emerged as a potential target for NSCLC therapy, either alone or in combination with PD-1." (PMID 37830607, 2023). "In the context of anti-tumor immunity, CD276 plays a dual role, acting as a T-cell stimulator to enhance T-cell activity, or as an inhibitor of T-cell function, thereby promoting tumor proliferation and invasion." (PMID 38260844, 2023). "Transmembrane CD276 is found not only on the surface of tumor cells, but also in cytoplasmic vesicles and in the nucleus." (PMID 37373167, 2023). "This experiment revealed a promising activity of CD276.V-CAR T cells in promoting clearance of orthotopic RMS tumor." (PMID 37924157, 2023). "It has been reported that CD276 is involved in the shaping and development of the tumor microenvironment (TME) by regulating T cell-mediated immune responses and is an attractive target for immunotherapies." (PMID 37981593, 2023). "At present, CAR‐T therapies targeting GD2, L1‐CAM, and CD276 and other tumor antigens have entered clinical trials." (PMID 38090056, 2023). "At the same time, the knockdown of CD276 expression reduces the adhesion, migration, and invasiveness of tumor cells." (PMID 36966168, 2023). "During the third week after RD injection, we observed RMS tumor eradication in 3/5 mice in the CD276 group." (PMID 37924157, 2023). "targeted IRDye700 to subcutaneous murine 4T1 tumors using a Fab portion of an antibody that attaches to CD276, an antigen specifically expressed on tumor cells." (PMID 37860012, 2023). "At week 2, 2/5 mice from the CD276 group and 2/5 from the Dual group showed a significantly smaller tumor burden, compared to the controls, visible also in the delayed tumor volume growth, and stagnation of bioluminescence signal." (PMID 37924157, 2023). "Further immunoinhibitory members of the B7 superfamily, which, similar to PD-L1, are expressed on the surface of a variety of normal tissue but also tumor cells, include B7-H3 (= CD276) and B7-H4 (= VCTN1)." (PMID 35941227, 2023). "The combination of CD276 inhibitors and PD-1/PD-L1 inhibitors in tumour treatment has become a hot research topic." (PMID 37974070, 2023). "The second highest expressed gene was CD276, which exhibited a significantly higher expression in all subgroups compared to non-tumor tissues." (PMID 36825029, 2023). "GPC2/CD276 BiCisCAR showed superior antitumor activity in vivo in animal testing, in which 33.3% of mice showed good tumor suppression or even tumor elimination activity." (PMID 38090056, 2023). "Upregulation of CD276 promoted the immune escape of tumor cells and reduced secretion of interleukin-2 (IL-2), tumor necrosis factor-alpha (TNF-α) and other cytokines." (PMID 36713082, 2023). "It is worth noting that CD276 is a recognized costimulatory immune checkpoint that exerts antitumor effects and that can inhibit tumor growth and metastasis." (PMID 36966168, 2023). "B7-H3 (CD276) is one family member that is upregulated in many cancer types and suggested to contribute to tumour–immune interactions." (PMID 37444640, 2023). "CD276 was initially characterized as a T cell-stimulating protein, although most current studies describe it as a T cell inhibitor that promotes tumor aggressiveness and proliferation." (PMID 37373167, 2023). "The results obtained have provided both novel insights into the functional role of CD276 in various types of tumor, especially in the case of GBM, and new knowledge that should be beneficial for the optimization of cancer immunotherapy." (PMID 36717836, 2023). "Our anti-CD276 monoclonal antibody (mAb) with cross-activity to both human and mouse receptors showed high surface binding, effective drug delivery and tumor-specific targeting in flow cytometry, confocal microscopy, and in vivo imaging system analysis." (PMID 37830607, 2023).
tumor (continued). "Emerging evidence shows that CD276 plays a key role in tumor progression, treatment resistance and poor prognosis." (PMID 38260829, 2023). "In Rh4-tumor bearing mice, CD276/FGFR4 Dual-CAR T cells showed a similar complete eradication as CD276.V-CAR T cells." (PMID 37924157, 2023). "During week 2, bioluminescence imaging revealed a reduction in tumor size in 1/5 mice from the CD276 group and in 1/5 mice from the F8-FR4 group, compared to the controls." (PMID 37924157, 2023). "CD276 suppresses the cytotoxic effect of T cells on tumours and is involved in the immune escape of tumour cells." (PMID 37974070, 2023). "Expression of vascular endothelial growth factor (VEGF) in tumor cells is mediated by the soluble form of CD276, suggesting that the combination of anti-CD276 and anti-VEGF drugs is a potential therapeutic approach." (PMID 37373167, 2023). "Some research studies had attested that high expression of CD276 had been confirmed to be probably related to the immune escape of tumor cells, and its overexpression in tumor cells had a strong interference and metastasis ability." (PMID 36105106, 2022). "Most of the tumor immunity-related genes, including PD-L1 (CD274), PD-1 (CD279), CTLA4, and B7H3 (CD276), were at a higher expression level in the high-risk group." (PMID 36267281, 2022). "CD276, also known as B7 homolog three protein (B7-H3), is recently considered a T cell inhibitor that promotes tumor proliferation and invasion." (PMID 36338975, 2022). "GPC2/CD276 BiCisCAR exhibits superior antitumor activity to tumor cells expressing either GPC2 or CD276." (PMID 35852863, 2022). "Augmented expression of CD276 is also observed in tumor blood vessels, and its overexpression correlates with poor prognosis in many cancers." (PMID 35852863, 2022). "Previous studies have reported the upregulation of CD276 in tumor plays essential roles in tumorigenesis." (PMID 36451812, 2022). "In oral squamous cell carcinoma (OSCC), CD276 is involved in tumor proliferation regulation, mainly via glycometabolism." (PMID 36358792, 2022). "Two other studies aim to investigate the role of omburtamab, a murine IgG1 monoclonal antibody, in recognizing CD276 (also known as B7-H3) and actively introducing it into the tumor by CED." (PMID 36140466, 2022). "Previous studies have shown that the expression of CD276 in tumor tissue is highly correlated with poor prognosis and survival time." (PMID 36175880, 2022). "This is in line with other reports pointing towards the role of CD276 in tumor cell proliferation, but it contrasts with the results obtained with the UM-UC cells investigated here." (PMID 35563359, 2022). "CD276 hindrance CD8+ T cells anti-tumor effects were improved with the elimination of CSCs by anti-CD276 immunotherapy, thus inhibiting tumor growth and spread." (PMID 35982868, 2022). "In parallel, CD276 is overexpressed in tumour tissue and is involved in the shaping and development of TME, while members of the TNF family are thought to regulate cell differentiation, survival, and programmed death and are associated with the immune system." (PMID 35860689, 2022). "CD276 blockade remodels tumor heterogeneity, reduces epithelial-mesenchymal transition, inhibits tumor growth and lymph node metastases." (PMID 36494785, 2022). "CD276-CAR NK cells or blocking CD276 with anti-CD276 antibody often rescues the anti-tumor ability of NK cells." (PMID 35514986, 2022). "It has been shown that miRNA-128 inhibits the expression of CD276, and high levels of CD276 promote tumor growth; furthermore, CD276 promotes tumor angiogenesis and increases the expression of VEGFA by activating the NF-κB pathway." (PMID 36358792, 2022). "One of the most promising recently discovered tumor targets is B7-H3 (CD276), highly expressed by several tumors and upregulated by IFN-γ." (PMID 35205760, 2022).
tumor (continued). "Meanwhile, we show the IHC staining of NRP1, HAVCR2, HHLA2CD44, TNFRSF18, TNFSF14, TNFRSF8, and CD276 in tumor tissues and normal tissues." (PMID 35685438, 2022). "When planning for tumor therapy, by targeting tumor cells by anti-CD276 therapy, underscoring CD276 expression by immunohistochemistry should take the seeming discrepancies between total CD276 protein in the cell versus on the cell surface into account." (PMID 35563359, 2022). "CD276, also known as B7-H3, has upregulated expression in many cancer cells and related with tumor cells by pathological angiogenesis." (PMID 36120433, 2022). "CD276 is a receptor that is overexpressed in various tumor cells and tumor vasculature but with limited expression in normal tissues." (PMID 36119019, 2022). "As CD276+ cells were mainly located at the peripheral tumor region, indicating a protective role of CD276 for immune-mediated killing, similar to our observation with NK cells." (PMID 36268020, 2022). "In line with recent studies, we found that the presence of specialized endothelial cells, expressing high levels of CD276 and Plvap promoted both tumor delivery and tumor cell-specific delivery of NPs." (PMID 36494816, 2022). "The combination of blocking CD276 and PD-1 using antibodies successfully inhibited tumor growth and increased tumor-infiltrated CD8+ T and NK cell levels." (PMID 36699466, 2022). "In LUAD, Ets-like protein 1 (ELK1) works as a transcription factor that binds to CD276 and regulates its expression, further promoting tumor proliferation and EMT process in the A549 cell line." (PMID 36358792, 2022). "CD276 is extensively overexpressed on tumor cells and tumor vasculature, and serves as a hazardous marker in GBM as it mediates immunosuppression via inhibiting activity of NK cells, inducing invasion and differentiation of tumor cells." (PMID 35135556, 2022). "Originally identified as a T cell co-stimulatory molecule, CD276 (B7 family) expression on tumor cells was found to prevent T cell and NK cell activity In addition, similar to our observation, high tumoral CD276 expression correlated with poor outcome as well." (PMID 36268020, 2022). "And recent studies have reported that CD276 had functions on T-cell co-inhibition contributing to tumor cell evasion." (PMID 35928223, 2022). "Among these, a type I transmembrane protein CD276, recently identified as a promising target for tumor immunotherapy, is notable." (PMID 35211173, 2022). "Conversely, MAP4K4 depletion decreased PM association of proteins involved in tumor immune evasion (CD155, CD276, and HLA-G), in solute influx regulation (CLIC1, SLCs, and ABCCs) and cell migration (CD155 and CD276)." (PMID 35296518, 2022). "The protumoral activity derived from MDSCs is driven by several molecules present in the tumor as the macrophage migration inhibitory factor, B7 homolog 3 protein, also known as CD276, or signal transducer and activator of transcription 3 (STAT3)." (PMID 36338755, 2022). "As compared to apparently healthy tissue, CD276/B7H3 expression was higher in primary tumor tissues in various cancer subtypes." (PMID 36550153, 2022). "B7-H3 (CD276; has a role in the regulation of the T-lymphocytic immune response, a role in increasing the survival of tumor cells through inhibition of cell lysis initiated by natural killer cells) is a new member of the B7 costimulatory molecule family." (PMID 35330327, 2022). "CD276 was highly expressed on the surface of HNSCC and acted as an immune checkpoint to enable cancer stem cells to evade the surveillance of the immune system, while blocking CD276 can effectively enhance T-cell-mediated anti-tumor immunity." (PMID 35942287, 2022). "In a high-risk cohort, a new-found checkpoint NRP1 (neuropilin-1) was reported as an immune response suppressor to cancer gathered higher expression, as well as CD276, which was proven to participate in tumor immune evasion in HNSCC." (PMID 35432535, 2022).
tumor (continued). "CD8+ lymphocytes recovered the cytotoxic potential against CSCs when anti-CD276 antibodies were infiltrated, hindering the spread of cells to lymph nodes and the tumor progression in animal models of HNSCC." (PMID 35982868, 2022). "For example, the expression of PD-L1 and B7-H3 (also known as CD276) in tumor cells can stimulate aerobic glycolysis in tumor cells by activating the PI3K/AKT/mTOR pathway." (PMID 36034789, 2022). "CD276 is expressed in multiple tumor lines, macrophages, and tumor-infiltrating dendritic cells, which can suppress autoimmunity." (PMID 36035176, 2022). "The elevated expression of CD276 on tumors contributes to the suppression of anti-tumor T-cell responses and correlates with poor prognosis." (PMID 35563359, 2022). "As a recently discovered immune checkpoint protein, B7-H3 (also known as CD276) has become a potential target for tumor immunotherapy." (PMID 36203966, 2022). "We also assessed the relationship between CD276 expression in tumor cells and clinical factors such as the response to initial therapy and overall mortality." (PMID 34680929, 2021). "A pan-cancer analysis of coagulome and TME environment across multiple tumor samples highlighted the positive correlation of CD276 to PAI-1 and uPA56." (PMID 34290311, 2021). "CD276 is a member of the B7 family of immunoregulatory proteins and is overexpressed in several tumor types." (PMID 34073720, 2021). "Retifanlimab, an anti-PD-1 antibody, and enoblituzumab, an anti-CD276, were evaluated in combination in multiple tumor types cohorts." (PMID 33747915, 2021). "B7-H3, also known as CD276, is an immune checkpoint molecule and immunoregulatory protein, which participates in tumor microenvironment shaping and development." (PMID 35096881, 2021). "The large body of data indicates a strong correlation between CD276 overexpression in tumor and poor patient prognosis." (PMID 34290311, 2021). "Another study conducted on a cohort of patients treated for clear cell renal cell carcinoma (ccRCC) reported that CD276 expression was detected in 17% of tumor cells and 95% of tumor vasculature." (PMID 33842369, 2021). "Recently, a number of studies have shown that CD276 is expressed in tumor vascular endothelial cells, suggesting that CD276 is related to tumor angiogenesis." (PMID 33842369, 2021). "Total protein expression is often regulated on the transcript level and tumor grade-depended elevation of CD276 transcripts and CD276 total protein were found in BC." (PMID 33845814, 2021). "CD276 can directly participate in the regulation of immunity and various malignant behaviors of tumor cells." (PMID 33842369, 2021). "Overall, the CD276 expression in tumor cells was significantly higher than that in healthy tissue (p < 0.0001)." (PMID 34680929, 2021). "This review summarizes the available evidence to the expression of CD276 in tumors and its regulation mechanism, CD276 in immune micro-environment, effect on tumor progression, and its potential therapeutic effect for malignancies." (PMID 33842369, 2021). "GFP-transduced WM115 tumor spheroids were grown according to protocol and CD276-CAR NK-92 cells were subsequently added in tissue culture-treated wells with 5.0 μm pore size." (PMID 33925968, 2021). "We found that COL1A1 and CD276 showed significantly higher expression in tumor sites than in the adjacent non-tumor samples." (PMID 33850663, 2021). "Multiple studies suggest a possible connection between poor clinical prognosis in patients with high CD276 expression on tumor cells and lower tumor infiltrated lymphocytes such as CD8+ T cells, which implies an immune-modulatory role of CD27619–22." (PMID 34290311, 2021). "CD276 targeted CAR T-cells were shown to have anti-tumor activity in pediatric solid tumor xenografts, depending on surface target density." (PMID 33918733, 2021). "In spheroid-monocyte or -macrophage coculture, CD276 signaling comes not only from tumor but also from MDMs." (PMID 34290311, 2021).